MIR6824 (microRNA 6824)
Synonyms: hsa-mir-6824
Gene: MicroRNA gene on chromosome 3 (48,633,636 to 48,633,698, reverse strand). Ensembl gene ENSG00000284364.
Homologues: Orthologues: chimpanzee MIR6824 (100% identical).